ENSG00000284691 (novel zinc finger protein)
Synonyms: LOC728743
Gene: Protein-coding gene on chromosome 7 (150,400,702 to 150,412,470, forward strand). Ensembl gene ENSG00000284691.
Gene Ontology:
Molecular function: DNA-binding transcription factor activity; RNA polymerase II cis-regulatory region sequence-specific DNA binding; DNA binding
Biological process: regulation of transcription by RNA polymerase II; regulation of gene expression
Cellular component: nucleus
Homologues: Orthologues: mouse AI854703 (94% identical), rat RGD1559747 (93% identical). Paralogues in human: ZNF34 (42% identical), ZNF287 (42% identical), ZNF774 (42% identical), ZNF852 (42% identical), ZKSCAN7 (41% identical), ZNF17 (41% identical), ZNF467 (41% identical), ZNF530 (41% identical), ZNF572 (41% identical), ZNF527 (41% identical), ZNF768 (41% identical), ZNF214 (40% identical), and 39 more.